GPC5 (glypican 5)
Diseases named in the same sentence as GPC5 in open-access papers (continued):
Sharing a sentence is not in itself a finding about the gene and the disease.
cancer (19 papers, 2013 to 2025). A tumor composed of atypical neoplastic, often pleomorphic cells that invade other tissues. "In summary, GPC5, a pivotal tumor suppressor gene across multiple malignancies, demonstrates a compromised anti-cancer efficacy post-mutation." (PMID 40352786, 2025). "The GPC5 gene is located on chromosome 13q31.3, a region that is frequently mutated in many types of cancers." (PMID 33902495, 2021). "Thus, germline GPC5 mutations may not only confer cancer risk but also predict immunotherapy resistance." (PMID 40352786, 2025). "Suppression of miRNA-4295 leads to upregulation of GPC5 expression, inhibiting cancer cell invasion." (PMID 39200178, 2024). "Glypican-5 (GPC5) is a member of heparan sulfate proteoglycans and reportedly involved in the regulation of cancer." (PMID 37830596, 2023). "We found a number of genes involved in G protein-coupled receptor signaling (ARAP2, LPHN2, LPHN3, EPHA4, ADGRL2, and GPC5) consistent with observations in pan-cancer studies." (PMID 35538064, 2022). "We also found copy number loss of cancer genes such as CCNE1, MAF, MAFB, MYC, ZNF479, and MGMT and copy number gain of FOXA2, CDH10, and GPC5 in at least two WDPM cases." (PMID 32545767, 2020). "Furthermore, GPC5 is pivotal in orchestrating the initiation, proliferation, migration, and invasion of cancer cells by activating signaling pathways such as Wingless/Integrated (Wnt), aryl hydrocarbon receptor (AHR) and Hedgehog." (PMID 40352786, 2025). "Although further verification is required, these findings suggest that GPC5 may become one of the critical regulators of cancer." (PMID 40688491, 2025). "Using a similar method to produce mAb against GPC5 may clarify the relationship between GPC5 and glycosylation in cancers." (PMID 40688491, 2025). "G5Mab-1 can be a valuable tool for versatile analysis of GPC5 in cancer research." (PMID 40688491, 2025). "In future studies, we intend to identify whether cancer-specific GPC5 structures and modifications exist by further developing anti-GPC5 mAbs using the same strategy." (PMID 40688491, 2025). "However, inhibition of GPC-1 expression also led to a slight increase in the expression of GPC-5, which can also contribute to cancer progression." (PMID 31391540, 2019). "So far, the role of GPC5 related to cancer is far from clear." (PMID 27806326, 2016). "The effects of GPC5 expression on cancer cell migration were assessed." (PMID 24260047, 2013). "Furthermore, GPC5 is expressed in some cancers, but whether it functions as a cancer-promoting or -suppressing factor remains unclear." (PMID 40688491, 2025). "Notably, the role of GPC5 varied across different cancer types." (PMID 27806326, 2016). "Therapeutically, these findings highlight the potential utility of Wnt pathway inhibitors in managing GPC5-mutant LUAD cases, while also providing a molecular framework for future investigations into glypican family members in cancer biology." (PMID 40352786, 2025). "GPC5 regulated the expression of CTDSP1 (C-terminal domain small phosphatase-1) and played a central role in the suppression of cancer progression." (PMID 37830596, 2023). "For instance, comparison between normal liver and kidney tissue and cancer involving these organs revealed high expression of GPC3 in liver hepatocellular carcinoma (LIHC) and low expression of GPC5 in kidney renal clear cell carcinoma (KIRC)." (PMID 36944188, 2023). "Here we outlined the remarkable features of HSPGs, such as GPC1, GPC4, GPC5, SDC1, SDC2, SDC3 and HSPG2, and some HSPG-related proteins like heparanase and SULF1/2, in cancer diagnosis." (PMID 34249755, 2021). "Furthermore, GPC5 may be involved in NSCLC metastasis through enhancing cancer cell migration." (PMID 24260047, 2013). "Like GPC5, GPC3 regulates many cancer-progressive cascades, including Wnt, hedgehog, and FGF." (PMID 40688491, 2025).
cancer (continued). "The mean migration rates of cancer cells transfected with pRNAT-shRNA-GPC5-1 were reduced compared with the controls in A549 (P<0.001) and H3255 (P=0.001), while the migration rate of SPC-A1 with GPC5 overexpression was higher than that of the control (P=0.001)." (PMID 24260047, 2013). "Compared with GPC-1, GPC-2, GPC-3, and GPC-5, few studies have investigated the mechanism and prognostic significance of GPC-4 and GPC-6 expressions at the mRNA level in malignant tumors, and no related reports have been found in HCC." (PMID 33902495, 2021). "Here, a cancer-wide GPC expression study, using clinical cancer patient data in The Cancer Genome Atlas, reveals net upregulation of GPC1 and GPC2 in primary solid tumors, whereas GPC3, GPC5 and GPC6 display lowered expression pattern compared to normal tissues." (PMID 36944188, 2023).
infection (4 papers, 2020 to 2025). The state of being infected such as from the introduction of a foreign agent such as serum, vaccine, antigenic substance or organism. "Glypican 5 (Gpc5) is associated with processes related to neuroinflammation 38, and Four-Jointed Box Kinase 1(Fjx1) is associated with infection." (PMID 40303348, 2025). "An additional study also reported successful infection of HepG2-NTCP cells with an HBV genotype D virus isolated from serum to determine the effect of glypican-5 (GPC5) expression on HBV entry." (PMID 32175289, 2020). "Furthermore, the expression of HBcAg and known infection-promoting factors including glypican 5 (GPC5), peroxisome proliferator–activated receptor alpha (PPARA), and CCAAT/enhancer-binding protein alpha (CEBPA) was detected." (PMID 34631680, 2021).
neurological diseases (2 papers, 2015 to 2023). "However, as a note of interest, these CNVs included the NDUFB3, NIF3L1, PPEF2, CACNA2D1 and GPC5 genes, which are expressed in the brain and/or have been implicated in neurological disorder." (PMID 25585696, 2015). "By consulting relevant literature, 6 genes related to neurodevelopmental and neurological diseases (GPC5, CA10, DSCAM, IL1RAPL2, CNTN2, and SPOCK3) were verified by ELISA method." (PMID 37539343, 2023). "Finally, six genes/proteins related to neurodevelopmental and neurological diseases (GPC5, CA10, DSCAM, IL1RAPL2, CNTN2, and SPOCK3) were verified by ELISA." (PMID 37539343, 2023).
adenocarcinoma (1 paper, 2013). A common cancer characterized by the presence of malignant glandular cells. "A recent GWAS suggested that genetic variants at 13q31.3 modulate GPC5 expression that had been downregulated in the adenocarcinomas in patients who had never smoked." (PMID 24260047, 2013).
GPC5 also shares sentences with these, for which no sentence is quoted: pancreatic cancer (3 papers); schizophrenia (2); adenoma (1); autoimmune diseases of the thyroid (1); bipolar disorder (1); breast tumors (1); diabetes (1); focal segmental glomerulosclerosis (1); glioma (1); glomerular disease (1); Huntington disease (1); IgA-nephropathy (1); immune deficiency (1); kidney cancer (1); kidney tumor (1); liposarcoma (1); melanoma (1); membranous nephropathy (1); neuroblastoma (1); neurodegenerative disease (1); Neuroendocrine Tumors (1); Obesity (1); Parkinson disease (1); renal disease (1); scrapie (1); Simpson-Golabi-Behmel syndrome (1); Stroke (1); sudden cardiac arrest (1); Usher syndrome (1).